ADAMTS5 (ADAM metallopeptidase with thrombospondin type 1 motif 5)
Diseases named in the same sentence as ADAMTS5 in open-access papers (continued):
Sharing a sentence is not in itself a finding about the gene and the disease.
heart failure (2 papers, 2021 to 2024). Inability of the heart to pump blood at an adequate rate to meet tissue metabolic requirements. "Previously, adenoviral overexpression of glypican-6 in cultured cardiomyocytes was shown to increase protein synthesis and induce hypertrophy and heart failure signature genes, suggesting glypican-6 as a relevant ADAMTS1 and ADAMTS5 target in cardiac development." (PMID 38750698, 2024).
laryngeal carcinoma (2 papers, 2015 to 2017). Carcinoma that arises from the laryngeal epithelium. "Notably, this finding is in harmony with previous studies having demonstrated a similar role of ADAMTS-5 in laryngeal cancer." (PMID 25786261, 2015).
liver fibrosis (2 papers, 2017 to 2024). "Moreover, both ADAMTS-5 and -9 cause turnover of proteoglycans in liver fibrosis." (PMID 29137610, 2017). "For example, versican expression and its cleavage via multiple ADAMTS enzymes, including ADAMTS5, are dysregulated during liver fibrosis and recovery." (PMID 39510178, 2024).
lymph node metastasis (2 papers, 2020 to 2023). "High expression of ADAMTS5 is a potent biomarker for lymphatic invasion and lymph node metastasis in CRC." (PMID 33258470, 2020).
aging (1 paper, 2021). A developmental process that is a deterioration and loss of function over time. "Thus, it is considered that degrading enzymes of biglycan and decorin can promote skin aging, and this study newly suggests possible roles of ADAMTS5 as a degrading enzyme of biglycan and decorin." (PMID 33573338, 2021).
cerebrovascular disease (1 paper, 2021). "In conclusion, our findings indicate that ADAMTS-5 is downregulated in human IA, and compensatory ADAMTS-5 administration inhibits IA development and rupture with potentially important implications for treating this cerebrovascular disease." (PMID 33934089, 2021).
chondrosarcoma (1 paper, 2020). A malignant cartilaginous matrix-producing mesenchymal neoplasm arising from the bone and soft tissue. "ADAMTS-4 and ADAMTS-5 levels were increased by 83.7 and 82.5%, respectively, in IL-1β-treated human chondrosarcoma cell line SW1353." (PMID 33321982, 2020). "Compared with IL-1β-treated human chondrosarcoma cell line SW1353, ADAMTS-4 and ADAMTS-5 expression were decreased dose dependently in the 20 μg/mL CZE and 0.4 μg/mL linarin treatments." (PMID 33321982, 2020).
colitis (1 paper, 2020). Inflammation of the colon. "Stainings for Adamts1, Adamts5, and Bmp1 showed similar distribution patterns as the MPO-staining, indicating that these proteases are contributed not by the colon epithelium, but by invading neutrophils/monocytes on colitis induction." (PMID 32160911, 2020).
colon cancer (1 paper, 2020). "A study found that ADAMTS5 overexpresses colon cancer cells to inhibit their invasion and migration." (PMID 32884571, 2020).
coronary stenosis (1 paper, 2019). Narrowing of the coronary artery lumen diameter. "This study is aimed at examining the relationship between the plasma ADAMTS-5 levels and the severity of coronary stenosis in patients with CAD." (PMID 31929842, 2019). "In our study, we aimed to detect the expression of ADAMTS-5 in humans with CAD and assayed its predictive power for the severity of coronary stenosis." (PMID 31929842, 2019). "Furthermore, we also tested the plasma levels of ADAMTS-5 and assayed its correlation with CAD as well as its predictive power for the severity of coronary stenosis." (PMID 31929842, 2019).
Fabry disease (1 paper, 2025). Fabry disease (FD) is a progressive, inherited, multisystemic lysosomal storage disease characterized by specific neurological, cutaneous, renal, cardiovascular, cochleo-vestibular and cerebrovascular manifestations. "Conversely, genes crucial for ECM integrity and maintenance, including ADAMTS5, LOXL1, COL1A1, and COL6A2, were all down-regulated in the patient hURECs, indicating dysregulated ECM dynamics, as previously observed in Fabry disease." (PMID 40673439, 2025).
focal segmental glomerulosclerosis (1 paper, 2020). A renal disorder characterized by sclerotic lesions in the glomeruli. "Notably, ADAMTS5+ inflammatory infiltrates were not unique to IgAN as the enzyme was also present in membranous nephropathy biopsies and focal segmental glomerulosclerosis lesions." (PMID 32917786, 2020).
Hypercholesterolemia (1 paper, 2022). An increased concentration of cholesterol in the blood. "Intra-articular anti-ADAMTS5 antibody slowed down the progression of OA in a dose-dependent manner in a murine OA model with hypercholesterolemia." (PMID 35168639, 2022). "Therefore, our findings suggest that hypercholesterolemia might also affect ADAMTS5 expression in the glenohumeral synovium." (PMID 35168639, 2022). "Hypercholesterolemia may alter MMP1 and ADAMTS5 expression in the synovium of the glenohumeral joint." (PMID 35168639, 2022). "Hypercholesterolemia may alter MMP1 and ADAMTS5 expression in synovium of the glenohumeral joint." (PMID 35168639, 2022). "Therefore, hypercholesterolemia altered synovial MMP1 and ADAMTS5 levels in the glenohumeral joint." (PMID 35168639, 2022).
influenza (1 paper, 2016). An acute viral infection of the respiratory tract, occurring in isolated cases, in epidemics, or in pandemics; it is caused by serologically different strains of viruses (influenzaviruses) designated A, B, and C, has a 3-day incubation period, and usually lasts for 3 to 10 days. "Here, we use a combination of in vitro and in vivo models to show that ADAMTS5 enzymatic activity plays a key role in the development of influenza-specific immunity." (PMID 27855162, 2016). "We also assessed CD8+ T cell numbers in MLN of influenza-infected Adamts5-/-Vcan+/hdf (versican reduced) mice to determine resumption of egress." (PMID 27855162, 2016). "Additionally, a qPCR time-course analysis of ADAMTS enzyme expression in the lungs of influenza-infected WT and Adamts5-/- mice was also performed and shown in S4 Fig for general reference." (PMID 27855162, 2016). "Increased influenza-specific DbNP366-372 and DbPA224-233 CD8+ T cell numbers were also detected by tetramer staining in the spleen of Adamts5-/-Vcan+/hdf versican reduced) mice at day 10 p.i. when compared to Adamts5-/-Vcan+/+ controls." (PMID 27855162, 2016). "Careful analysis revealed comparable numbers of total CD8+ T cells and influenza-specific CD8+NP366-372+ and DbPA224-233+ (by tetramer and ICS) in the MLN of Adamts5-/-Vcan+/hdf (versican reduced) and C57.BL6 control mice." (PMID 27855162, 2016). "The lack of influenza-specific CD8+ T cells in the periphery of Adamts5-/- mice suggested possible accumulation of cells in the draining lymph nodes of the lung, such as the MLN." (PMID 27855162, 2016). "In our studies, we demonstrate that mice lacking Adamts5 have fewer influenza-specific lymphocytes in the lung and spleen following infection." (PMID 27855162, 2016).
intracranial aneurysm (1 paper, 2021). "A mouse model of elastase injection was used to study the effects of ADAMTS-5 on IA that may not recapitulate all aspects of a human intracranial aneurysm, particularly regarding actual hemodynamics and mechanical properties in the cerebral vessel." (PMID 33934089, 2021).
intracranial hemorrhage (1 paper, 2021). Bleeding within the SKULL, including hemorrhages in the brain and the three membranes of MENINGES. "According to the statistical data, the rate of intracranial hemorrhage was significantly higher in the high-dose ADAMTS-5 inhibitor treatment group than in the low-dose group and DMSO-treatment control group." (PMID 33934089, 2021). "Compared with the fish embryos of the control group (exposed to 0.1% DMSO, v/v), which exhibit normal development, intracranial hemorrhage was observed in the group treated with ADAMTS-5 inhibitor (ATS5-in 0.5 μg/mL) from 36 hpf to 72 hpf." (PMID 33934089, 2021). "In order to further verify the functions and role of ADAMTS-5 in cerebral blood vessels, we used the specific ADAMTS-5 inhibitor in zebrafish embryos and observed intracranial hemorrhage in the midbrain and hindbrain of the larvae." (PMID 33934089, 2021). "The results demonstrated that ADAMTS-5 inhibition may weaken the integrity of the brain blood vessels, leading to intracranial hemorrhage." (PMID 33934089, 2021). "Additionally, experiments performed on zebrafish animal model demonstrated that functional inhibition of ADAMTS5 in vascular tissue might weaken the integrity of the cerebral vessel wall, leading to intracranial hemorrhage." (PMID 33934089, 2021). "Thus, the prominent phenotypes of intracranial hemorrhage were caused by ADAMTS-5 deficiency, revealing that the absence of ADAMTS-5 may lead to specific defects in the maintenance of vascular integrity." (PMID 33934089, 2021).
myocardial infarction (1 paper, 2020). Gross necrosis of the myocardium, as a result of interruption of the blood supply to the area, as in coronary thrombosis. "Studies have shown that the fibrinolytic pathway involving D-dimer may predict myocardial infarctions in adults and ADAMTS-5 is a extracellular matrix protease." (PMID 33066786, 2020).
non-alcoholic steatohepatitis (1 paper, 2018). "In addition, Adamts5-/- mice appeared to be protected from non-alcoholic steatohepatitis (NASH) when kept on a Western type diet." (PMID 29293679, 2018).
peritonitis (1 paper, 2020). Inflammation of the peritoneum (tissue that lines the abdominal wall and covers most of the organs in the abdomen). "For instance, although the possible function of ADAMTS5 on C3 is unknown, the ability of leukocyte elastase to process complement is known since the late 1970s, whereas a more recent study found that MMP12 was able to process and inactivate C3 in murine peritonitis." (PMID 32917786, 2020).
Pleural effusion (1 paper, 2013). The presence of an excessive amount of fluid in the pleural cavity. "In addition we detected a homozygous deletion at 21q that simultaneously deleted the metallopeptidases ADAMTS1 and ADAMTS5 that was present only in the pleural effusion populations." (PMID 23372550, 2013).
renal fibrosis (1 paper, 2022). A final common manifestation of a wide variety of chronic kidney diseases characterized by glomerulosclerosis and tubulointerstitial fibrosis. "In the UUO mice model, exogenous HGF restored the expression of Adamts5 and ameliorated renal fibrosis induced by Men1 deficiency." (PMID 35968938, 2022).
skin aging (1 paper, 2021). The gradual irreversible changes in structure of skin that occur as a result of the passage of time.. "We presented one possibility that ADAMTS5 could be one of the new anti-skin aging targets, and it is suggested that inhibiting this enzyme may contribute to suppressing skin aging." (PMID 33573338, 2021).
status epilepticus (1 paper, 2021). Status epilepticus is defined as a continuous seizure lasting more than 30 min, or two or more seizures without full recovery of consciousness between any of them. "Following status epilepticus, transcripts of matrix metalloproteinases such as MMP3, ADAMTS5, ADAMTS8, and ADAMTS9 were induced." (PMID 35185464, 2021).
synovitis (1 paper, 2014). Inflammation of a synovial membrane. "Although bevacizumab did not decrease IL1B expression significantly, we suggest that the decrease in MMP13 and ADAMTS5 expression levels contributed to the absence of synovitis." (PMID 25230745, 2014).
thyroid cancer (1 paper, 2022). "First, we verified the expression of 9 immune-related prognostic factors, AKAP12, APOC1, TIMP3, ADAMTS9, ANK2, HTRA3, SYNDIG1, ​​ADAMTS5 and DACT1, in 11 thyroid cancer cell lines in the CCLE database." (PMID 36591507, 2022).
tubulointerstitial nephritis (1 paper, 2020). "Notably, the mix of ADAMTS5-affected matrix proteins was enriched in basement-membrane components including laminins (LAMA/LAMB/LAMC), collagen-6 (COL6A1/A2), collagen-12 (COL12A1), AGRN, nidogen-1 (NID1), and TINAG (tubulointerstitial nephritis Ag)." (PMID 32917786, 2020).
ulcerative colitis (1 paper, 2023). An inflammatory bowel disease involving the mucosal surface of the large intestine and rectum. "Immunohistochemical analysis of ADAMTS-1, ADAMTS-4, ADAMTS-5, and IL-17 A protein in the colon tissues of healthy human control and those with ulcerative colitis." (PMID 37798683, 2023). "Taken together, these findings suggest that IL-17 A may promote the breakdown of the intestinal wall in ulcerative colitis by stimulating the high expression of ADAMTS-5." (PMID 37798683, 2023).
uterine infection (1 paper, 2009). "The uterine infection was also associated with a marked upregulation of several ADAM and ADAMTS metalloproteases, primarily ADAMTS2, ADAMTS5, ADAMDEC1 and ADAM28." (PMID 19956711, 2009).
vascular malformation (1 paper, 2025). A non-neoplastic disorder that is the result of defects of vascular morphogenesis. "In addition, increased ADAMTS5 expression in endothelial cells appears to act with CCM1 loss of function, resulting in larger vascular malformations." (PMID 40332397, 2025).
virus infection (1 paper, 2023). "The top 4 were “Cell matrix adhesion and organization” (COL6A1, COL6A2, COL18A1, JAM2, ADAMTS5 and POFUT2), “Immune/virus infection response” (MX1 and MX2), “Histone modification and chromatin remodeling” (NRIP1) and “Glycerolipid and lipid metabolism” (AGPAT3)." (PMID 38095646, 2023).
ZIKV infection (1 paper, 2023). "On the other hand, mRNA levels for MMP-9, ADAMTS-4, and ADAMTS-5, which have been reported associated with PNN degradation, and gelatinase/collagenase activity were not significantly elevated in the brain during ZIKV infection." (PMID 37496706, 2023).
tumor (35 papers, 2006 to 2026). "Altered expression of ADAMTS5 is associated with human carcinogenesis and tumor progression." (PMID 34386813, 2021). "The results of the subcutaneous tumor model in nude mice showed that tumor weight and volume increased after silencing of ADAMTS5 (p < 0.05)." (PMID 41704852, 2026). "ADAMTS5 has been reported to either promote or inhibit tumour formation in a context‐dependent manner." (PMID 40164572, 2025). "ADAMTS5 major substrates are the proteoglycans aggrecan and versican, which support the structural integrity of the cartilage and the tumor microenvironment." (PMID 41381706, 2025). "Specifically, the increased expression of ADAMTS5 facilitated by the LRRC75A-AS1-mediated sponging of miR-370-5p highlights a potential pathway contributing to tumor invasion and metastasis." (PMID 39575481, 2025). "ADAMTS5 is involved in extracellular matrix remodeling, and promotes tumor invasion and metastasis in various cancer types." (PMID 39575481, 2025). "The six-BMRGs risk score, comprising CD151, CTSA, MMP1, ROBO3, ADAMTS5 and MEP1A, was established for the prediction of clinical prognosis, tumor microenvironment characteristics, and immunotherapy response in HCC." (PMID 39070142, 2024). "Adamts5 is a new metalloproteinase belonging to the ADAMTS family, which is associated with tumor proliferation and migration." (PMID 36902425, 2023). "We previously reported a novel role of ADAMTS5 as an angiogenesis inhibitor, suppressing tumor growth." (PMID 35197459, 2022). "The MHCF1 unique mutations consisted of protein misfolding (Hsp-related genes) and acetylcholine receptor (Chrnb4 and Chrm5) genes that possibly act on cancer cell processes, and tumor suppressor (Adamts1 and Adamts5) and cell cycle (Aurkb and Bub1) genes." (PMID 34158541, 2021). "Adamalysins genes/ A distintegrin and metalloproteinase with thrombospondin motifs (ADAMTS) family genes, ADAMTS1 (FC = −9.4, p = 0.009), and ADAMTS5 (FC = −5.7, p = 0.05) were significantly down-regulated in tumours, as compared to controls." (PMID 31292488, 2019). "In IDC I–II samples, Fibulin-2 was barely detected in tumor cell masses and ADAMTS-5 was present in masses of epithelial cells." (PMID 28099917, 2017). "Western blot analysis using a set of normal-tumor paired samples also revealed that ADAMTS-5 is highly expressed in the tumor samples analyzed." (PMID 28099917, 2017). "More functional and clinical studies are needed to fully understand the participation of ADAMTS-5 in tumor processes." (PMID 28099917, 2017). "ADAMTS5 is a metalloproteinase with the ability to slow tumor growth and diminish tumor angiogenesis, together with reduced tumor cell proliferation and increased tumor cell apoptosis." (PMID 25481245, 2014). "Literature on ADAMTS5 in CRC cancer is extremely limited with only one study reporting this gene as one of the most hypermethylated in tumor as compared with the surrounding normal colonic mucosa." (PMID 24988459, 2014). "The molecular interactive signaling of miR-145 in BLCA has been tested, and its anti-tumor effect may be attributed to the negative regulation of ADAMTS5." (PMID 40937200, 2025). "It is well documented that ADAMTS5 shows tumor type specific functions." (PMID 37238942, 2023). "Regarding tumor-related processes, both ADAMTS-4 and ADAMTS-5 are associated with a protumor role." (PMID 31508361, 2019). "Hence we validated gene expression of MMP1, MMP3, MMP11, MMP13, MMP14, ADAMTS1 and ADAMTS5 genes belonging to metallopeptidase activity, using qPCR in 67 tumours." (PMID 31292488, 2019). "Our data strongly suggest that the cleavage by aggrecanases, but especially by ADAMTS-5, could influence the balance between pro- and anti-tumor effects elicited by Fibulin-2." (PMID 28099917, 2017). "This could indicate that ADAMTS-4 exerts a less relevant role than ADAMTS-5 in the metastatic processes of certain tumor types." (PMID 28099917, 2017).